H2AX (H2A.X variant histone)
Diseases named in the same sentence as H2AX in open-access papers (continued):
Sharing a sentence is not in itself a finding about the gene and the disease.
lung carcinoma (continued). "To investigate whether La/SSB associated with DNA damage markers, we examined the expression of La/SSB and ɣ‐H2AX by fluorescence microscopy in untreated and irradiated lung cancer cells." (PMID 34636174, 2022). "CDP138 was unravelled to enhance radiosensitivity in lung cancer cells by increasing γ‐H2AX foci in CDP138‐depleted lung cancer cells after exposure to radiation, and γ‐H2AX has been regarded as a useful marker of cellular radiosensitivity after single and fractionated irradiation in vivo." (PMID 32476275, 2020). "Increased formation of phospho-H2AX observed in human lung carcinoma cells exposed to ionizing radiation and decreased levels of phospho-H2AX with increased expression of DNMT1 by histone deacetylase (HDAC) inhibitors further support our results in malignantly transformed renal epithelial cells." (PMID 27655674, 2017). "Furthermore, to explore the functions of miR-493 in repair of cDDP-induced DNA damage, we evaluated the levels of H2AX phosphorylation on serine 139 (γ-H2AX) in lung cancer cells." (PMID 28859669, 2017). "Indeed, similar to knockdown of TDP2 (siTDP2), knockdown of ERK3 (siERK3) greatly increased H2AX phosphorylation (γ-H2AX, a marker of DNA damage) induced by either Etoposide or Teneposide in H460 lung cancer cells." (PMID 26701725, 2016). "Similarly, knock down of ERK3 (shERK3/siCtrl), TDP2 (shGIPZ/siTDP2) or both (shERK3/siTDP2) increased γ-H2AX in A549 lung cancer cells treated with etoposide." (PMID 26701725, 2016). "To test whether our results allow generalization, we transiently transfected the human lung cancer cell line H1299 with GFP-tagged H2AX, H2AX-S139A and empty vector." (PMID 18616816, 2008). "However, the Rad51-positive foci, in comparison to the H2AX-positive but Rad51-negative foci, obviously have more correlative power for the radiation sensitivity of lung cancer cell lines." (PMID 15785736, 2005). "In addition, Ɣ-H2AX regulates apoptosis in lung cancer cells." (PMID 34696659, 2022). "Additionally, salvicine mediates the activation of the following pathways: ataxia telangiectasia mutated (ATM) kinase, ataxia telangiectasia and Rad3-related (ATR) kinase, and histone H2AX; therefore, the complete experimental trail occurs in lung carcinoma A549 cells." (PMID 35719997, 2022). "In addition, phosphorylation of histone H2AX (γH2AX) and the formation of 53BP1 foci were quantified in Calu-6 and A549 human lung cancer cells as early biomarkers of DNA-DSB formation, following 10 Gy of radiation treatment in the presence and absence of NU5455 (5 μM)." (PMID 31581151, 2020). "In an NNK-induced in-vivo model of lung cancer, EGCG regulated epigenetic mechanism by downregulating DNMT1 along with phospho-histone H2AX (γ-H2AX) and p-AKT reduction." (PMID 40760406, 2025). "We first irradiated lung cancer cells with increasing doses of radiation, and the presence of La/SSB protein and ɣ‐H2AX PLA foci was examined." (PMID 34636174, 2022). "In in vivo model of lung cancer, EGCG epigenetic action in down-regulating DNMT1 is accompanied by phospho-histone H2AX (γ-H2AX) and p-AKT reduction." (PMID 30563268, 2018). "Previous work in our laboratory demonstrated that SUV39H2-mediated H2AX methylation increases the formation of γ-H2AX in lung cancer cells and that inhibition of SUV39H2 enhances chemosensitivity of lung cancer cells to cisplatin or DOX." (PMID 30159125, 2018). "Three lung cancer lines (A549, H460 and LL2) were irradiated with different X‐ray doses or X‐radiated with a 5 Gy dose and examined at different time‐points post‐irradiation for DNA DSB in the form of γ‐H2AX and Rad51 foci." (PMID 34636174, 2022).
lung carcinoma (continued). "Our study shows that the overexpression of P130cas downregulates radiosensitivity of lung cancer cells in vitro and in vivo and decreases the levels of cleaved PARP, cleaved caspase-3 and γ-H2AX induced by ionizing irradiation, which indicates the inhibition of apoptosis and DNA damage." (PMID 36088346, 2022). "Because γ-H2AX foci and Rad51 foci were co-localized in the cells treated with VAL-083, VAL-083–induced DNA DSBs were suggested to be repaired by HR, which was consistent with the previous report using lung cancer." (PMID 34073837, 2021). "The overexpressed NLRP3 could mimic silica-induced DNA damage and mutagenic double-strand breaks that were documented as increased levels of γ-H2AX, p-CHK2 in airway epithelial cells and closely related to the occurrence of lung carcinomas." (PMID 34660289, 2021). "However, the AM-101 enhancement of γ-H2AX is not observed in the lung cancer brain-metastatic cell line UW-lung-16, although radiation alone does enhance γ-H2AX in this line." (PMID 39335139, 2024). "Consistently, transfection of siKLC4, combined with cisplatin or etoposide, markedly enhanced the accumulation of γ-H2AX at the protein level, indicating that KLC4 depletion may considerably increase the genotoxic effect of cisplatin and etoposide in aggravating DNA damage in lung cancer cells." (PMID 32457423, 2020).
glioma (52 papers, 2010 to 2026). A benign or malignant brain and spinal cord tumor that arises from glial cells (astrocytes, oligodendrocytes, ependymal cells). "CypA can also form a DNA degradation complex with AIF and γ-H2AX, which can cause chromatinolysis and promote glioma cell necroptosis." (PMID 36038617, 2022). "In order to further demonstrate the mechanism of TIGAR knockdown-induced radiosensitization in TrxR1-overexpressing glioma cells, DNA damage-associated γ-H2AX foci and the cellular distribution of Trx1 were illustrated by immunofluorescence assay." (PMID 28338004, 2017). "By using caffeine and wortmannin, as well as DNA dependent protein kinase (DNA-PK) –proficient and-deficient cells, Human glioma cell line M059K and M059J, the kinases responsible for H2AX phosphorylation induced by GAA were investigated." (PMID 25530717, 2014). "As the cytotoxicity of TMZ is known to be associated with O6MeG lesions, which cause DSBs, we compared the level of phospho-histone H2AX, an indicator of DSBs, in glioma and melanoma cells treated with TMZ or TMZ-Se." (PMID 22496897, 2012). "Since it is clear that DNA-PK participated in the process of phosphorylation of H2AX, DNA dependent protein kinase (DNA-PK)- proficient and –deficient cells, human glioma cell line M059K and M059J, were used to observe the effect of GAA-induced H2AX phosphorylation." (PMID 25530717, 2014). "Thus, to evaluate whether axitinib treatment could trigger the DDR in glioma cells, we initially investigated the presence of γ-H2AX (H2AX), Ser139 phosphorylated variant of histone 2A associated with DNA double-strand breaks." (PMID 27926485, 2017). "The results demonstrated that QX302 treatment significantly elevated γ-H2AX levels in the nuclei of glioma cells compared to the control and TMZ treatments." (PMID 41513607, 2026). "Immunofluorescence assays showed increased γ-H2AX levels in QX302-treated glioma cells, indicating substantial DNA damage." (PMID 41513607, 2026). "As expected, consistent with the trend of γ-H2AX expression levels, the ROS levels in glioma cells also decreased significantly after TMZ treatment." (PMID 40914135, 2025). "SMURF2 interacts with and destabilizes H2AX, which plays a central role in DNA repair and genome stability, in glioma cells." (PMID 35017630, 2022). "Proliferation, colony and 3D spheroid formation assays, western blotting, comet assay, γ-H2AX staining were used to evaluate the anti-glioma effects of the top-ranked candidates." (PMID 32714096, 2020). "Activation of AKT can enhance DNA damage repair (DDR) by promoting γ-H2AX foci resolution in irradiated glioma cells, whereas downregulation of AKT facilitates unrepairable DNA double strand breaks (DSB) in irradiated U251 glioma cells." (PMID 32899427, 2020). "IP3 diffusion through gap junctions contributed to bystander signaling as demonstrated by the reduced γ-H2AX spread in C6 glioma cells expressing IP3-impermeable Cx26 channels." (PMID 32188841, 2020). "Accordingly, we next stained glioma cells with γ-H2AX dye after co-culture with the macrophages and found that the amount of DSBs was highly increased in glioma cells." (PMID 31216715, 2019). "In contrast, compared with the controls, overexpression of G0S2 in glioma LN229 and U87 glioma cells significantly prevented IR-induced γ-H2AX foci formation in these cells." (PMID 30953555, 2019). "First, we tested the potential of Dbait to induce DNA-PK activation in human glioblastoma cell lines by assaying phosphorylated H2AX proteins by Western blot in the 9 high grade glioma cell lines." (PMID 31275862, 2019).
glioma (continued). "Here, our results support this notion and show that G0S2 overexpression inhibited 53BP1 ubiquitination and upregulated 53BP1 foci cell formation in glioma cells, and thereby reduced γ-H2AX expression and γ-H2AX foci cell formation in response to irradiation." (PMID 30953555, 2019). "Western blot analysis showed that in all the glioma cell lines except in the DNA-PK deficient MO59J cell line, Dbait induced phosphorylation of H2AX." (PMID 31275862, 2019). "All these data indicated that TOPK blocked TMZ-induced glioma cell apoptosis through increasing γ-H2AX." (PMID 29487691, 2018). "Herein we demonstrated that the TKI axitinib induces DNA damage response (DDR) characterized by γ-H2AX phosphorylation and Chk1 kinase activation leading to G2/M cell cycle arrest and mitotic catastrophe in U87, T98 and U251 glioma cell lines." (PMID 27926485, 2017). "The regulation of key DDR and cell cycle proteins, including Chk1, γ-H2AX and p21(Waf1/Cip1) was also studied in glioma cell lines." (PMID 27926485, 2017). "DNA dependent protein kinase (DNA-PK) - proficient and –deficient cells, human glioma cell lines M059K and M059J, were also used to evaluate the kinases responsible for GAA induced H2AX phosphorylation." (PMID 25530717, 2014). "The mean nuclear IRS of phospho-H2AX indicating DSB accumulation was lowest in gliomas from SDHA versus ATM, BRCA2, and FANCA GV carriers, although the differences were not statistically significant, possibly because SDHA variants are least directly linked to impaired DSB repair." (PMID 41546701, 2026). "γ-H2AX assay showed that IDH1-mutant glioma cells had higher radiosensitivity than wild-type." (PMID 37952042, 2023). "Radiosensitivity of glioma cells was detected by γ-H2AX after 5 Gy radiation." (PMID 37952042, 2023). "Interestingly, WB showed that the expression of γ-H2AX, a biomarker for DNA double-strand breaks, was upregulated in glioma cells with MYH9 knockdown." (PMID 37770914, 2023). "Therefore, these indicated that shikonin induced nuclear translocation of AIF and γ-H2AX formation in glioma cells in vivo." (PMID 36038617, 2022). "Additionally, the radio-sensitivity of glioma U-251 cells increased, due to the NaBt-induced reduction in the Ku70 protein and an increase in the y-H2AX foci, which decreased the ability for double-strand break (DSB) repair." (PMID 34944565, 2021). "It has been reported that the pre-treatment of glioma cells with a pyrrole-imidazole (Py-Im) polyamide prior to exposure to ionizing radiation resulted in a delay in the resolution of phosphorylated γ-H2AX foci that are indicative of the delayed repair of double-stranded breaks." (PMID 34768867, 2021). "Interestingly, phospho-H2AX induction was accompanied by Ser345-Chk1 phosphorylation already at 3 h after exposure to axitinib that declined at later time points in all glioma cell lines." (PMID 27926485, 2017). "The DNA damage and apoptosis induced by TRPML-2 loss increased Ser139 H2AX phosphorylation and induced caspase-3 activation; furthermore, knock-down of TRPML-2 in T98 and U251 glioma cell lines completely abrogated Akt and Erk1/2 phosphorylation, as compared to untreated cells." (PMID 27248469, 2016). "In vitro functional results, from our study, indicated that an up- regulation of miR-370-3p sensitizes GBM cells to TMZ, which causes suppression in the ability of DNA repair, activation of H2AX, enhanced rate of apoptosis, and suppressed growth of glioma cells." (PMID 27595933, 2016). "In our study, we found that the level of phosphorylated histone H2AX in the gliomas of the Per2-knockdown group after X-ray irradiation was significantly lower than the control virus or normal control groups at all time points, indicating reduced DNA double strand breakage." (PMID 27036047, 2016).
glioma (continued). "The results showed that exposure of glioma cells to either BO-1051 or irradiation (2 Gy) resulted in a significant increase of γ-H2AX foci at 1 h that was sustained for 6 h, and then the γ-H2AX foci declined to almost basal level at least 24 h after irradiation or drug removal." (PMID 21244709, 2011). "Furthermore, we showed recently that H2AX phosphorylation is completely blocked at early times (≤ 15 min) after irradiation when both drugs are applied to glioma cells." (PMID 20844317, 2010). "Both in vitro and in vivo tumor xenograft studies confirmed that TPTEP1 knockdown enhanced glioma cell stemness and radioresistance-associated gene expression, such as OCT4, aldehyde dehydrogenase 1 (ALDH1), and γ-H2AX (the γ phosphorylated form of the histone H2AX)." (PMID 41431719, 2026). "Meanwhile, the expression levels of γ-H2AX were decreased with the extension of TMZ treatment, indicating that glioma cells develop TMZ resistance." (PMID 40914135, 2025). "Correspondingly, TMZ-induced glioma cell death, nuclear translocation of AIF and upregulation of γ-H2AX were all enhanced when BNIP3 was knocked down." (PMID 33879840, 2021). "In the present study, we observed that there was a higher expression of ATRX in TMZ resistant glioma cells compared to parental cells, and that ATRX was positively correlated with DNA damage repair marker γ-H2AX in GBM specimens." (PMID 32194873, 2020). "To further demonstrate that G0S2 regulates glioma radioresistance through 53BP1, we knocked down 53BP1 using shRNAs in U87/G0S2 and LN229/G0S2 cells and determined γ-H2AX expression and γ-H2AX foci formation in response to IR." (PMID 30953555, 2019). "Immunofluorescence assays (IF) evaluated γ-H2AX foci for DSB repair kinetics in human astrocytes and T98G glioma cells." (PMID 29899825, 2018). "Increased H2AX phosphorylation, caspase-3 cleavage, reduced Rad51 and RIP1 expression, as well as sustained IκBα expression were also observed in mouse glioma xenografts treated with the cyclo-RGD inhibitor and TMZ, confirming the molecular mechanism in vivo." (PMID 27487141, 2017). "The increase in phosphorylated H2AX foci (γH2AX) formation, an indicator of DNA damage, persisted in TMZ-treated glioma cells with stable knockdown BRCC3 expression, suggesting that BRCC3 gene deficiency is associated with DNA repair impairment." (PMID 25337721, 2014). "Moreover, nuclear levels of γ-H2AX, phospho-ATM and phospho-DNAPKcs were all up-regulated in shikonin-treated gliomas." (PMID 36038617, 2022). "Here, we found that treatment of glioma cells with axitinib triggers the DDR, evidenced by increased levels of phosphorylated H2AX and Ser345-Chk1, leading to cell cycle arrest at G2/M phase and accumulation of polyploid glioma cells undergoing mitotic catastrophe." (PMID 27926485, 2017). "Moreover, the levels of p-ATM, p-H2AX, PARP1 and PAR were all increased in DPT-treated gliomas." (PMID 37186123, 2023). "Secondly, the presence of C6-Glioma does not seem to induce tumour-bystander effects that could modify the degree of γ-H2AX formation." (PMID 25799425, 2015). "The two low-grade glioma tissues analyzed were almost negative for the markers, with the exception of p-ATM and γ-H2AX, poorly positive at level of mitoses." (PMID 25892134, 2015). "Moreover, both senescent glioma cells (identified with GFAP, γ-H2AX, and P21 positive, and Lamin B1 negative expression) and TAMs (identified with IBA1, γ-H2AX, and P21 positive, and Lamin B1 negative expression) were reduced by GDC-0879." (PMID 40781221, 2025).